CTLA4 (cytotoxic T-lymphocyte associated protein 4)
Diseases named in the same sentence as CTLA4 in open-access papers (continued):
Sharing a sentence is not in itself a finding about the gene and the disease.
melanoma (continued). "CTLA-4 was the first immune checkpoint that was successfully targeted with the CTLA-4 mAb ipilimumab in heavily pretreated melanoma patients, and this treatment prolonged overall median survival in two independent studies." (PMID 28588576, 2017). "Various case studies and clinical trials have demonstrated that there is less toxicity and prolonged progression-free survival from the use of PD-1 checkpoint blockade compared to CTLA-4, in advanced melanoma, for instance." (PMID 29033936, 2017). "Anti-CTLA-4 ipilimumab was the first “immune checkpoint” inhibitor that led to tumor regression and a survival benefit for patients with advanced melanoma and was therefore approved by the FDA in 2011." (PMID 28611299, 2017). "In patients with advanced melanoma, CTLA-4 inhibition has been observed to produce durable response rates in approximately a quarter of treated patients." (PMID 29179523, 2017). "Benign lymphadenopathy has also been described as a radiographic finding in melanoma patients treated with anti-CTLA-4 therapy, the most common pattern reported to be sarcoid-like and in a bilateral hilar and mediastinal distribution." (PMID 27660712, 2016). "When mice bearing irradiated or unirradiated tumors were treated with radiation and anti-CTLA-4 antibody, an anti-tumor response was observed, but resistance was detected due to T cell exhaustion and the upregulation of PD-L1 on the melanoma cells." (PMID 27854240, 2016). "Immune checkpoint blockade antibodies targeting CTLA-4 and PD-1 have become a major breakthrough in cancer treatments for some patients with advanced melanoma." (PMID 27764796, 2016). "Recent studies have confirmed the survival benefit of ipilimumab (a monoclonal antibody that targets CTLA-4) in patients with advanced melanoma and non-small-cell lung cancer." (PMID 26918337, 2016). "Blockade of CTLA-4 with the mAb ipilimumab has already benefited thousands of people with advanced melanoma, a disease that typically used to kill people in less than a year." (PMID 27151159, 2016). "Ipilimumab, an anti-CTLA-4 monoclonal antibody, is the first agent ever proven to improve survival in advanced melanoma." (PMID 26767073, 2016). "Adverse events (AE) related to anti PD-1/PD-L1 antibody as a single therapy and to a greater extent when combined with anti CTLA-4 or BRAFi are well documented in patients with melanoma and lung cancer." (PMID 26943572, 2016). "As a consequence, the combination of an A2A receptor antagonist and anti-CTLA-4 or anti-PD-1 synergistically inhibited (metastatic) tumor growth in breast cancer (4T1) and melanoma (B16F10) preclinical models." (PMID 27847783, 2016). "Results from clinical trials assessing monoclonal antibodies targeting PD-1 (pembrolizumab/nivolumab) and CTLA-4 (ipilimumab) in cancers other than melanoma, i.e., lung cancer and ovarian cancer, have been very promising." (PMID 27301245, 2016). "We conclude that α-CD137 and α-PD-1 antibodies were most effective in enhancing SBRT-induced tumor growth delay in this mouse melanoma model, outperforming the ability of IL-2, or the combination of α-CTLA-4 and α-PD-1 to synergize with SBRT." (PMID 27160390, 2016). "Anti-CTLA-4 mAb and anti-CD40 mAb administered with liposome-encapsulated peptide vaccine or an adenoviral vector encoding melanoma antigen induced effective tumor-specific CD8+ T cells with no detrimental side effects." (PMID 27827885, 2016). "It is interesting that long-term survival of patients with advanced melanoma has been achieved by using Tremelimumab, an anti-CTLA-4 antibody." (PMID 27683579, 2016). "In a phase 1 clinical trial with advanced melanoma patients, the combination of anti-CTLA-4 and anti-PD-1 increased the response rate up to 53% patients with severe treatment-related adverse events." (PMID 27917371, 2016). "Ipilimumab is a recombinant, IgG1 human monoclonal antibody targeting CTLA-4 that is FDA-approved for the treatment of melanoma." (PMID 27904752, 2016).
melanoma (continued). "In summary, anti-PD-1 is less toxic yet more effective than anti-CTLA-4 and is also effective in the treatment of non-melanoma tumors." (PMID 27847783, 2016). "Anti-CTLA-4 treatment has also been studied in non-melanoma tumors, demonstrating an 8% partial response rate in patients with metastatic renal cell carcinoma (RCC) in a phase II study." (PMID 27847783, 2016). "Vaccination with recombinant adenovirus encoding melanoma antigen delayed tumor growth in 30%–40% of mice, while vaccination in combination with anti-CD40 and anti-CTLA-4 mAbs induced complete response." (PMID 27827885, 2016). "The combination of anti-PD-1 and anti-CTLA-4 antibodies increased the clinical response in advanced melanoma patients with a recent FDA approval." (PMID 27234522, 2016). "Lastly, prophylactic vaccination with a highly attenuated Trypanosoma cruzi strain expressing a cancer-testis antigen, NY-ESO-1 (CL-14-NY-ESO-1) combined with anti-CTLA-4 was highly effective in controlling the development of an established melanoma." (PMID 27827885, 2016). "Very recently, this has been experimentally proven in animal models as well as in melanoma patients treated with the anti–CTLA-4 monoclonal antibody, ipilimumab." (PMID 26943571, 2016). "T cell checkpoint blockade with antibodies targeting programmed cell death (ligand)-1 (PD-1/PD-L1) and/or cytotoxic T lymphocyte-antigen 4 (CTLA-4) has improved therapy outcome in melanoma patients." (PMID 27160390, 2016). "Antagonism of CTLA-4 with ipilimumab therefore blocks co-receptor interaction leading to activation of the innate immune system, stimulating an immune response against melanoma tumor cells." (PMID 27777775, 2016). "Overall, patients who had tumors bearing a high frequency of somatic mutations like melanoma, NSCLC, and MSI-H colorectal cancer were significantly more likely to achieve clinical benefit from checkpoint blockade including CTLA-4 and PD-1 inhibitors." (PMID 27895917, 2016). "For example, CTLA-4 and PD-1 blockade are ineffective in the B16 mouse melanoma tumor model yet have demonstrated activity in human melanoma." (PMID 27610613, 2016). "Given what has been learned from melanoma, studies of CTLA-4 inhibition in patients with sarcoma should ideally include PFS or OS as primary endpoints with incorporation of immune-related response criteria." (PMID 27703409, 2016). "In the case of B16 melanoma, optimal outcome required sub-lethal irradiation and anti-CTLA-4 mAb injections in addition to adoptive T cell transfer (ACT)." (PMID 27626487, 2016). "High response rates have especially been obtained by the combination of CTLA-4 and PD-1 and as a consequence this combination was approved in 2015 for the treatment of melanoma." (PMID 27847783, 2016). "A phase I clinical trial with ipilimumab (anti-CTLA-4) combined with nivolumab (anti-PD1) reported tumor regression in 50 % of treated patients with advanced melanoma." (PMID 27151159, 2016). "Currently, the combination of anti-CD27 (varlilumab) with anti-CTLA-4 (ipilimumab) or anti-PD-1 (nivolumab) is investigated in respectively patients with melanoma (NCT02413827) and solid tumors (NCT02335918) in phase I/II studies." (PMID 27847783, 2016). "In a more recent study, it was established that immuno-checkpoint inhibitors, including anti-programmed cell death protein 1 (anti-PD-1) and anti-cytotoxic T-lymphocyte antigen-4 (anti-CTLA-4) antibodies, were important treatment options for advanced melanoma." (PMID 27756356, 2016). "Conversely, therapeutic strategies that eliminate the Tregs to modulate Treg activity (e.g., anti-CD25 mAb and CTLA-4 antagonists) have had some success in treating melanoma patients." (PMID 26964534, 2016). "In autoimmune diseases such as RA, anti-TNF biologics are now routinely administered and improve life quality for many patients, and, in cancer, we have recently witnessed the success of combined anti-CTLA4 and anti-PD-L1/PD-1 in the treatment of melanoma." (PMID 26997761, 2016).
melanoma (continued). "Preclinically, combined treatment with a TFG-β receptor kinase inhibitor I and anti-CTLA-4 synergistically inhibited primary and metastatic tumor growth in a melanoma model (BRAFV600EPTEN−/−)." (PMID 27847783, 2016). "A high frequency of Melan-A or NY-ESO-1 specific CD8+ T cells were detected in melanoma and prostate cancer patients who showed a clinical response to anti-CTLA-4 therapy." (PMID 26788324, 2016). "Herein, we report the case of a melanoma patient treated with sequential BRAF/MEKi (dabrafenib plus trametinib) followed by the anti CTLA-4 antibody ipilimumab who achieved a pathological complete response." (PMID 27447748, 2016). "In one study of 198 melanoma patients undergoing treatment with anti-CTLA-4 antibody, 21 % of the patients developed enterocolitis, requiring high dose systemic corticosteroid treatment, and five patients developed perforations or required colectomy." (PMID 27071457, 2016). "When combined with an alphavirus replicon particle-based vaccine encoding the TRP2 melanoma antigen, anti-GITR agonist antibody induced significantly enhanced therapeutic efficacy compared to anti–CTLA-4 mAb plus TRP2 vaccine." (PMID 27827885, 2016). "T cell checkpoint inhibitors like α-CTLA-4 and α-PD-1/PD-L1 mAbs have revolutionized treatment of melanoma." (PMID 27160390, 2016). "According to more recent studies, combining T cell co-inhibitory blockade with anti-CTLA-4 and active co-stimulation with anti-4-1BB promotes rejection and regression of B16 melanoma and prostate tumors, respectively, in the context of a suitable vaccine." (PMID 27151159, 2016). "In 2011, the United States Food and Drug Association approved two new treatments for advanced, unresectable melanoma - the antagonist cytotoxic T-lymphocyte antigen 4 (CTLA-4) antibody, ipilimumab, and the targeted BRAF inhibitor, vemurafenib." (PMID 27777775, 2016). "A 27.3% response rate was obtained with anti-CD40 (CP-870893) plus anti-CTLA-4 (tremelimumab) in a phase I study in melanoma patients (NCT01103635)." (PMID 27847783, 2016). "Overall, double immune-checkpoint blockade with anti-CTLA-4 anti-PD-1 is currently the most effective combination approach and is approved for the treatment of melanoma." (PMID 27847783, 2016). "Monoclonal antibodies against PD-1 and CTLA-4 are approved for advanced melanoma, non-small cell lung cancer, and renal cell carcinoma, and are being investigated in numerous other cancers." (PMID 27660712, 2016). "This is consistent with recent publications showing patients with melanoma tumors having ATMLs less than 100 to have significantly less clinical benefit from anti-CTLA-4 therapy." (PMID 27776519, 2016). "In support of this, long-established preclinical melanomas resistant to dual PD-L1 and CTLA-4 blockade are eradicated by vaccination in approximately 33% of mice, but eradicated by vaccination combined with anti-PD-L1 in 80% of mice." (PMID 27057463, 2016). "Ipilimumab is a human monoclonal IgG1 antibody against CTLA-4 that has been shown to prolong the overall survival of advanced melanoma." (PMID 27570779, 2016). "Overall, long-term survival can be obtained with anti-CTLA-4 treatment in melanoma patients, but the toxicity is quite high and it is typically less effective in other tumor types." (PMID 27847783, 2016). "A phase I trial of combined nivolumab (anti-PD-1) and ipilimumab (anti-CTLA-4) in advanced melanoma showed an overall response of 40 % and objective responses in 53 % of patients treated with the maximal tolerated dose." (PMID 31093342, 2016). "The recent breakthrough of biologics against immune checkpoint inhibitors such as PD1 and CTLA-4 in melanoma has demonstrated unprecedented clinical responses due to reduced immune suppression." (PMID 27110718, 2016). "In melanoma, an increase in overall survival has been demonstrated with anti-CTLA-4 and PD-1 inhibition." (PMID 27532025, 2016).
melanoma (continued). "Unexpectedly, we found that CTLA4 expression in melanoma differentially correlates with CD8 T-cell levels in different tumors." (PMID 27549193, 2016). "Increased absolute T-cell counts and melanoma-specific CTLs have also been measured in cancer patients receiving the anti-CTLA-4 mAb Ipilimumab and seemed to correlate with a clinical benefit." (PMID 26110267, 2015). "The feasibility of this approach has recently been demonstrated in melanoma using combined CTLA-4 and PD-1 inhibition." (PMID 25901283, 2015). "Very recently, combined therapy\ of anti-PD1 (nivolumab) and anti-CTLA-4 (ipilimumab) showed improved efficacy in treating melanoma." (PMID 26648938, 2015). "CTLA-4 blockade for treatment of melanoma patients provoked grade 3 and grade 4 IRAE including autoimmune damages in colon, liver, and hormonal glands." (PMID 26167163, 2015). "Both PD-1 and CTLA-4 blockade have proven to be very effective in preclinical animal models of melanoma and some breast cancer models." (PMID 26300242, 2015). "For instance, recently melanoma cells were reported to mount resistance against anti-CTLA4 immunotherapy by up-regulating surface PD-L1 and thereby causing T cell exhaustion." (PMID 26682274, 2015). "Antibodies targeting cytotoxic T-lymphocyte antigen-4 (CTLA-4) and programmed death-1/programmed death ligand-1 (PD-1/PD-L1) are already being used clinically in a range of malignancies, including melanoma, where they have had very positive effects." (PMID 26633468, 2015). "In summary, combination immunotherapy with high-dose IL-2 and CTLA-4 blockade, compared to either monotherapy alone, improves therapeutic responses in the poorly immunogenic B16 murine melanoma model." (PMID 25992289, 2015). "A trial combining MEDI3617 and anti Ang2 antibody and tremelimumab (anti-CTLA4) in melanoma is enrolling participants (NCT02141542)." (PMID 26442214, 2015). "We are now exploring combined therapies of CXCL10-Ig with anti-PD1 or anti-CTLA-4 in a melanoma set-up." (PMID 26648938, 2015). "Targeting CTLA-4 with ipilimumab for melanoma immunotherapy was the first clinical demonstration of the physiological role of CTLA-4 acting as an immune checkpoint that controls T-cell reactivity." (PMID 26322044, 2015). "In humans, ipilimumab (α-CTLA-4) and nivolumab (α-PD-1) mAb combinational blockade has shown promise in clinical trials against advanced melanoma with 40-50% of patients achieving objective responses and a reduction in tumor burden." (PMID 25992292, 2015). "Immune checkpoint modulation has become a clinically relevant therapy approach in melanoma and lung cancer; in particular, anti-CTLA-4 antibody shows promising results in clinical trials in melanoma patients." (PMID 26079374, 2015). "Studies using the OX40 agonist in combination with either anti-4-1BB, anti-PD-L1, anti-CTLA-4, and immunization in sarcoma, melanoma, hepatoma, and breast cancer models have shown significant survival benefit by boosting the T-cell response." (PMID 26300242, 2015). "This assumption proved correct, as evident by the impressive anti-melanoma clinical responses achieved with anti-CTLA4/PD-1/PD-L1 antibodies (i.e. immune-checkpoint inhibitors or ICIs)." (PMID 26682274, 2015). "In line with this, blockade of CTLA-4 in the B16 melanoma model acts locally in the TME by inactivating Tregs in an Fc-dependent manner resulting in a favorable shift in the effector T cell/Treg ratio." (PMID 26500653, 2015). "Combination blockade of CTLA-4 and PD-1 in malignant melanoma has yielded objective response rates over 55% with nearly 90% of patients surviving at 2 years versus a 2-year survival in this population of <20% as recently as 2010." (PMID 26442210, 2015). "In two large initial phase III trials, the anti-CTLA-4 monoclonal antibody ipilimumab significantly prolonged survival and produced durable responses in patients with advanced melanoma." (PMID 25941561, 2015).
melanoma (continued). "Clinically, PD-1 and CTLA4 have been simultaneously targeted for the treatment of melanoma, and anti-tumor activity appears to be more robust than targeting each pathway alone." (PMID 25614821, 2015). "This combination immunotherapy did improve therapeutic responses over either CTLA-4 blockade or IL-2 monotherapy against the poorly immunogenic B16 melanoma." (PMID 25992289, 2015). "Here, B6 mice were challenged with poorly immunogenic B16 melanoma on day 0, and treated with CTLA-4 blocking antibody (100 μg/mouse) on days 3, 6, and 9, and IL-2 (100,000 units) twice daily on days 4–8, or both." (PMID 25992289, 2015). "The recently found astounding efficacy of combined anti-CTLA-4 and anti-PD-1 therapy in advanced melanoma patients argues in favor of targeting multiple pathways for future immunotherapeutic approaches." (PMID 26347741, 2015). "In these studies CTLA-4 blockade has yielded objective responses to such an extent that ipilimumab was FDA approved to treat metastatic or unresectable melanoma in 2011." (PMID 26236750, 2015). "The synergistic action of a CTLA-4 blocking Ab (tremelimumab) in combination with DC therapy has already been demonstrated in advanced melanoma patients and several other trials evaluating this approach are on the horizon." (PMID 26834740, 2015). "The clinical development of immune checkpoint blocking antibodies has been pioneered by the antibody ipilimumab (Yervoy®), which inhibits CTLA-4 and has demonstrated survival benefit in two randomized landmark trials in melanoma." (PMID 25901283, 2015). "This multi-institution immunotherapy trial for melanoma tested CTLA-4 blockade +/− the addition of GM-CSF in a 2-arm trial that included 245 melanoma patients, which was run with the support of the ECOG-ACRIN national cooperative group." (PMID 25806107, 2015). "In melanoma patients, blocking CTLA4 produced a host of immune-related toxic side effects (referred to as immune-related adverse events)." (PMID 25614821, 2015). "In a melanoma model, anti-CTLA-4 predominantly inhibits Treg cells in TIL but also reinvigorates exhausted PD-1 + Eomes + CD8 T cells." (PMID 26322044, 2015). "Promising immunotherapies have been developed for cancer: ipilimumab (CTLA-4 antibody) for melanoma and PD-1 and PD-L1 antibody for melanoma, renal cell carcinoma, and lung cancer." (PMID 25793623, 2015). "As the FDA recently approved both pembrolizumab and nivolumab for melanoma progressing after anti-CTLA-4 treatment with ipilimumab, more patients will soon receive anti-PD-1 therapy." (PMID 25901283, 2015). "Pioneering work by James Allison led to the development of ipilimumab, a fully human monoclonal antibody against cytotoxic T-lymphocyte-associated protein 4 (CTLA-4), which was approved by the FDA in 2011 for the treatment of patients with advanced melanoma." (PMID 26518223, 2015). "Ipilimumab, a monoclonal antibody directed against CTLA-4, was the first drug to show improved overall survival in patients with advanced melanoma and has also shown single-agent activity in other malignancies." (PMID 26709361, 2015). "Immune-modulating antibodies came to the forefront with anti-CTLA-4, programmed cell death-1 (PD-1) and PD-1 ligand 1 (PD-L1) pathway blocking antibodies that result in durable responses in a subset of melanoma patients." (PMID 26619946, 2015). "A total of one hundred and one (n = 101) AJCC Stage IV melanoma patients treated with anti-CTLA-4 Abs formed the study cohort." (PMID 26426340, 2015). "Ipilimumab is a fully human monoclonal antibody (IgG1) that promotes T-cell-mediated antitumor activity in patients with melanoma by blocking the interaction of CTLA-4 with CD80/CD86 and augmenting T-cell activation and proliferation." (PMID 26155423, 2015). "Almost 25 years after the CTLA-4 gene was cloned, clinical studies showing ipilimumab to significantly prolong overall survival in patients with advanced melanoma earned this agent FDA approval in March of 2011." (PMID 25992290, 2015).